RN7SL555P (RNA, 7SL, cytoplasmic 555, pseudogene)
Gene: Miscellaneous RNA gene on chromosome 20 (3,094,171 to 3,094,509, forward strand). Ensembl gene ENSG00000263905.
Homologues: Orthologues: chimpanzee Metazoa_SRP (99% identical), guinea pig Metazoa_SRP (53% identical), macaque Metazoa_SRP (52% identical). Paralogues in human: RN7SL1 (73% identical), RN7SL2 (73% identical), RN7SL3 (72% identical), RN7SL230P (70% identical), RN7SL7P (70% identical), RN7SL126P (69% identical), RN7SL127P (69% identical), RN7SL300P (69% identical), RN7SL478P (69% identical), RN7SL714P (69% identical), RN7SL113P (69% identical), RN7SL213P (69% identical), and 700 more.